CTLA4 (cytotoxic T-lymphocyte associated protein 4)
Diseases named in the same sentence as CTLA4 in open-access papers (continued):
Sharing a sentence is not in itself a finding about the gene and the disease.
brucellosis (4 papers, 2021 to 2024). Brucellosis is a bacterial infection that spreads from animals to people via unpasteurized dairy products or by exposure to contaminated animal products or infected animals. "In this study, the tissue expression profile of CTLA4 in goats was investigated, and the correlation between InDel polymorphisms in the CTLA4 gene and susceptibility to brucellosis in goats was examined." (PMID 39456732, 2024). "As a key candidate gene potentially linked to brucellosis risk, we conducted a statistical analysis of the frequency distribution of genotypes and alleles at the P1 and P2 loci of the CTLA4 gene within the goat population under study." (PMID 39456732, 2024). "Binary logistic regression analysis was used to investigate the associations between four genetic models (codominant, dominant, recessive, and allelic) and the risk of brucellosis at the P1 and P2 loci of the CTLA4 gene." (PMID 39456732, 2024). "Studies have shown that polymorphisms in the CTLA4 gene are linked to an increased risk of brucellosis in humans, but its association with brucellosis in goats remains unexplored." (PMID 39456732, 2024). "Therefore, the relationship between CTLA4 gene polymorphisms and brucellosis resistance in goats is worth exploring." (PMID 39456732, 2024). "Therefore, this study aimed to identify variant loci in the CTLA4 gene that may be linked to brucellosis risk in goats, offering valuable insights for breeding strategies to control brucellosis in these animals." (PMID 39456732, 2024). "The exhausted NK cells (NK_CD56(dim)) highly expressed multiple inhibitory molecules (e.g., LAG3, CD244, CTLA4) in brucellosis patients compared to healthy donors." (PMID 39135683, 2024). "The frequencies of Tregs and CTLA-4+ Tregs were higher in patients with chronic brucellosis than in healthy individuals (P = 0.026 and P = 0.011, respectively)." (PMID 34592958, 2021). "Increased serum TGF-β1 levels were positively correlated with Tregs, and CTLA-4 expression on Tregs further supported the critical role of TGF-β1 in mediating the reduced T cell function in patients with brucellosis." (PMID 34592958, 2021). "While CTLA4 gene variants have been linked to human brucellosis infection, research on their association with brucellosis in goats is lacking." (PMID 39456732, 2024). "This study showed that the designed vaccine containing CTLA-4 had high potency against Brucella, which could provide a reference for the future development of efficient brucellosis vaccines." (PMID 37493775, 2023). "Further analysis found that Th1 cells had the highest exhaustion scores in brucellosis patients, and highly expressed multiple inhibitory receptors (e.g., LAG3, CD160, CTLA4)." (PMID 39135683, 2024). "CTLA-4, GITR, and PD-1 were evaluated on Treg cells in acute brucellosis (n = 34), chronic brucellosis (n = 15), and HC (n = 29)." (PMID 34592958, 2021). "Multiple activation markers, such as CD69, MKI67, CCL5, CTLA4, IFNG and GZMB, were found to be enriched in the NK cells of brucellosis patients, indicating the presence of an activated NK cell response as a distinctive feature for brucellosis patients, especially for those at the acute stage." (PMID 39135683, 2024). "Importantly, CTLA-4 expression was elevated in patients with chronic brucellosis, and PD-1 and GITR were elevated in patients with acute and chronic brucellosis." (PMID 34592958, 2021).
bullous pemphigoid (4 papers, 2018 to 2026). Bullous pemphigoid (BP) is the most common form of autoimmune bullous dermatosis. "Exacerbation of pre-existing bullous pemphigoid has been mostly reported under anti-CTLA-4 agents." (PMID 37370736, 2023). "Several cases of bullous pemphigoid and bullous pemphigoid-like skin lesions have been described in patients under treatment with anti-PD-1 agents, whereas rare cases of bullous skin lesions have been reported after anti-CTLA-4 antibodies." (PMID 30693134, 2018).
cerebral malaria (4 papers, 2012 to 2025). A sequestration of Plasmodium falciparum in the brain, which can cause coma and/or seizures. "In this study, we determined the contribution of CTLA-4 and PD-1/PD-L to the regulation of T cell responses during Plasmodium berghei ANKA (PbA)-induced experimental cerebral malaria (ECM) in susceptible (C57BL/6) and resistant (BALB/c) mice." (PMID 22319445, 2012). "Thus, our study suggests that CTLA-4 may be much more effective than PD-1/PD-L1 at regulating CD4+ T cells particularly in this experimental model of cerebral malaria, although this hypothesis remains to be directly tested." (PMID 22319445, 2012). "For instance, in malaria infection, immune checkpoints such as PD-1 and CTLA-4 suppress T cell proliferation and inhibit IFN-γ production via distinct signaling pathways, thereby preventing immunopathology such as cerebral malaria." (PMID 40718479, 2025).
chronic granulomatous disease (4 papers, 2020 to 2023). Chronic granulomatous disease (CGD) is a rare primary immunodeficiency, mainly affecting phagocytes, which is characterized by an increased susceptibility to severe and recurrent bacterial and fungal infections, along with the development of granulomas. "Other monogenic conditions include dysfunction of NADPH oxidase complex, X-linked inhibitor of apoptosis (XIAP), lipopolysaccharide responsive beige-like anchor protein (LRBA), cytotoxic T lymphocyte-associated protein 4 (CTLA-4), STAT3, and chronic granulomatous disease." (PMID 33643966, 2020).
chronic GVHD (4 papers, 2015 to 2024). "However, for CD28’s inhibitory counter player CTLA-4 it has been shown that the 49G polymorphism, leading to comparatively weak B7-binding, is associated with enhanced T cell responses in vitro and a higher risk to develop chronic GvHD in vivo." (PMID 28690612, 2017). "In chronic GVHD, mBreg cells can provide protection by the suppressive effects and inhibit proliferation of effector T cells through IL‐10 secretion and cell‐to‐cell contact involving CTLA-4." (PMID 33343576, 2020).
cognitive decline (4 papers, 2022 to 2026). "Furthermore, immune-related hypophysitis, observed in up to 18% of patients treated with the CTLA-4 inhibitor ipilimumab, may cause pituitary dysfunction and hormonal imbalance, which can manifest clinically as fatigue, mood alterations, and cognitive decline." (PMID 41598630, 2026). "In AD patients, the correlation analysis showed an association between the decline in CD28 + T cells and the increase in CTLA-4 + T cells with cognitive decline, measured by the mini-mental state examination (MMSE), tau proteins and Amyloid-β, important AD biomarkers in cerebrospinal fluid (CSF)." (PMID 34427746, 2022).
colorectal adenocarcinoma (4 papers, 2019 to 2024). The most common type of colorectal carcinoma. "In our study, risk score was significantly negatively correlated with CTLA4, PDL1, and PDL2, indicating that female advanced colorectal adenocarcinoma patients with lower risk scores are more likely to benefit from immunotherapy of anti-CTLA4, anti-PDL1, and anti-PDL2." (PMID 38049474, 2023). "Consequently, our results prove that female advanced colorectal adenocarcinoma patients with lower risk scores are more likely to benefit from immunotherapy of anti-CTLA-4, anti-PDL1, and anti-PDL2 than those with higher risk scores." (PMID 38049474, 2023). "GAMT served as one of the components to predict the sensitivity of colorectal adenocarcinoma patients to immune therapy targeting PD-1 and CTLA-4." (PMID 38287304, 2024).
cutaneous T cell Lymphoma (4 papers, 2021 to 2023). "CTLA4-CD28 gene fusions have been preferably observed in AITL, PTCL-NOS, ATLL, and cutaneous T-Cell lymphomas and, therefore, may represent a potential target for anti-CTLA4 immunotherapy." (PMID 35330161, 2022). "The TNBC cell lines express high levels of PD-L1 and CTLA-4, but low levels of LAG-3, whereas the HuT-78 cells, derived from cutaneous T cell Lymphoma, express high levels of LAG-3." (PMID 35008285, 2021).
dengue (4 papers, 2016 to 2024). "In addition, a study demonstrated that a combination of TGF-β1 and cytotoxic T-lymphocyte antigen 4 (CTLA-4) was associated with susceptibility to severe dengue." (PMID 36297236, 2022). "However, other studies have shown that polymorphisms in the genes for CTLA-4 are associated with DHF and higher frequencies of Tregs from dengue progressors expressed CTLA-4, indicating that a closer investigation of the role of CTLA-4 in dengue pathogenesis is warranted." (PMID 38752787, 2024).
depression (4 papers, 2021 to 2025). "In the present study, many anti-depressant targets of EMO against depression were associated with the inflammatory response such as IL6, TNF, IL10, CRP, IL1B, CTLA4, ALB and IL2." (PMID 34051074, 2021). "An integrated analysis identified 434 preeclampsia-associated secretory protein genes and 1165 depression-related pathogenic genes, from which three signature biomarkers, CLEC3B, CTLA4, and PDPR, were ultimately determined via LASSO regression and random forest algorithms." (PMID 41409330, 2025).
diabetic ketoacidosis (4 papers, 2019 to 2024). The metabolic condition resulted from uncontrolled diabetes mellitus, in which the shift of acid-base status of the body toward the acid side because of loss of base or retention of acids other than carbonic acid is accompanied by the accumulation of ketone bodies in body tissues and fluids. "On the contrary, two more potential signals were detected, concerning chronic pancreatitis induced by anti-PD-1 (IC025 = 0.16) and diabetic ketoacidosis induced by anti-CTLA-4 (IC025 = 1.67)." (PMID 35431928, 2022).
glomerular disease (4 papers, 2019 to 2025). "Anti-cytotoxic T-lymphocyte-associated protein 4 (CTLA4) immunoglobulin (Ig), which is able to block both activating CD28 and inhibitory CTLA4 signaling, has been shown in preclinical and clinical investigations to have effects on glomerular disease." (PMID 33251233, 2020). "Due to the correlation of CD80 and CD86 expression in many glomerulopathies, the B7-1(CD80)-CTLA-4 and B7-2(CD86)-CTLA-4 interactions have been proposed as a molecular target in the treatment of these diseases." (PMID 31177287, 2019). "In addition, the therapeutic effects of abatacept, a CTLA4-immunoglobulin fusion protein (CTLA4-Ig) which blocks the interaction between B7-1 (APC) and CD28 (T cell), are still in uncertainty in glomerular diseases." (PMID 35710882, 2022). "First, both MCD and MN showed a broadly concordant upregulation of the PD-1/PD-L1, CTLA-4/CD86 and CD200/CD200R axes across all three levels when compared with healthy volunteers, indicating a globally enhanced inhibitory checkpoint tone in primary glomerulopathies." (PMID 41373530, 2025).
hemophilia A (4 papers, 2015 to 2024). The most common form of hemophilia characterized by spontaneous or prolonged hemorrhages due to factor VIII deficiency. "Recent investigations have shed light on CTLA-4’s involvement in autoimmune modulation, establishing it as a risk factor for inhibitor formation in inherited hemophilia A." (PMID 38920981, 2024). "Emerging evidence implicates CD4+ T cell activation in mediating this autoimmune response, with their involvement like that observed in congenital hemophilia A. Several genes such as HLA II DRB*16, DQB1*0502, and CTLA-4 + 49 are responsible for the pathogenesis of AHA." (PMID 38920981, 2024).
liver cirrhosis (4 papers, 2020 to 2024). "Chen's study in China revealed that the CTLA-4 +49G>A gene polymorphism of the GG genotype increased the risk of developing liver cirrhosis and HCC, while CTLA-4 -318 T>C of CC genotype increased the risk of persistent hepatitis B virus infection (Chenet al., 2014)." (PMID 37767077, 2022). "Genes related to senescence (e.g., PTPRC, TIGIT, and TNF) and exhaustion (e.g., PDCD1, CTLA4, LAG3, and TNFRSF9) were highly enriched in CD4+ and CD8 + T cells from the participants with liver cirrhosis." (PMID 37735474, 2023). "We found significantly higher expression of markers of T-cell senescence (e.g., PTPRC, TIGIT, and TNF) and exhaustion (e.g., PDCD1, CTLA4, LAG3, and TNFRSF9) in hepatic CD4+ and CD8 + T cells in participants with NASH or liver cirrhosis than in controls." (PMID 37735474, 2023).
lung disease (4 papers, 2021 to 2025). "LRBA is required for vesicular trafficking of CTLA4 and thus required for its cell-surface expression, resulting in similar phenotype as CTLA4 haploinsufficiency, although with more prominent lung disease." (PMID 40842819, 2025).
lymphoid neoplasm (4 papers, 2020 to 2024). A neoplasm composed of a lymphocytic cell population which is usually malignant (clonal) by molecular genetic and/or immunophenotypic analysis. "Additionally, this approach allows us to identify the effects of chronic inflammation, represented by PTGS2 levels, on the acute or lymphocytic tumor infiltrate, which is represented by CTLA4." (PMID 38201508, 2023). "Therefore, abnormal expression of CTLA-4 may play a role in the pathogenesis of malignant lymphoid tumors." (PMID 39464701, 2024).
mastitis (4 papers, 2011 to 2025). Inflammation of breast tissue during lactation or postpartum due to an obstructed duct or infection. "Indeed, the Kaplan-Meier survival curve analysis showed that the dairy cows with high expression of CTLA-4 at D0 and PD-1 at D-14 had a higher incidence of new IMIs by major mastitis pathogens through the first month of lactation." (PMID 38641805, 2024).
mesenchymal tumors (4 papers, 2018 to 2022). "In PyMT breast cancer models, epithelial tumors were susceptible to elimination by anti-CTLA-4 immunotherapy, whereas corresponding mesenchymal tumors were refractory to such treatment." (PMID 35582229, 2020). "Likewise, next-generation sequencing has defined subgroup-specific transcriptional profiles that correlate with different mechanisms of immune evasion, including increased PD-L1 and CTLA-4 among mesenchymal tumors." (PMID 30534602, 2018).
mismatch repair deficiency (4 papers, 2020 to 2025). "Anti-PD-1 (programmed death 1) and cytotoxic T-lymphocyte–associated antigen 4 (CTLA-4) immune checkpoint inhibitors (ICI) have been shown to benefit the mCRC patients with mismatch repair deficiency (dMMR) or high microsatellite instability (MSI-H)." (PMID 32268531, 2020). "Therefore, blocking CTLA4 in the context of inducing MMR deficiency in tumors can allow subdominant epitopes in those tumors to generate high-affinity T cell clones able to recognize even cryptic epitopes on tumor cells." (PMID 36068918, 2023). "Thus, strategies involving inducing MMR deficiency and anti-CTLA4 therapy may prevent disease recurrence following complete response in children." (PMID 36068918, 2023).
myeloid leukemia (4 papers, 2020 to 2023). A clonal proliferation of myeloid cells and their precursors in the bone marrow, peripheral blood, and spleen. "Cytotoxic T-lymphocyte-associated protein 4 (CTLA-4) functions as a negative regulator of T-cell activation and effector function and is expressed by myeloid leukemia cells." (PMID 32536937, 2020). "Finally, overexpression of both B7 proteins on AML cells is linked to poor prognosis, and blocking of CTLA-4/B7 interaction seems to be a promising strategy for therapy of myeloid leukemias." (PMID 33801964, 2021). "The significant differences in clinical outcomes in the two DAC-involved groups might be due to dose-dependent apoptosis in myeloid leukemia cells and synergistic cytotoxicity or chemosensitization, especially dose-dependent upregulation of PD-L1, PD-L2, PD-1, and CTLA4 expression." (PMID 34504785, 2021). "Co-stimulatory signals from myeloid leukemia cells enhance Th1 cell exhaustion, elevating immune checkpoints such as PD1, TIM-3, LAG-3, and CTLA-4." (PMID 37891580, 2023).
oropharyngeal cancer (4 papers, 2020 to 2023). Carcinoma, predominantly squamous cell, arising from the epithelial cells of the oropharynx. "Three markers, PD-1, PD-L1 and CTLA-4, related to immune therapy were not significantly different according to SOX2 expression in either HPV+ or HPV− oropharyngeal cancers (all p > 0.05)." (PMID 33182283, 2020).
penile cancer (4 papers, 2024 to 2025). A primary or metastatic malignant neoplasm that affects the penis. "The most studied immune checkpoints are PD-1/PD-L1 and CTLA-4, although their value as predictive biomarkers for treatment response remains inconclusive in many malignancies and also in penile cancer." (PMID 40822998, 2025). "We further hypothesized that STAT4 overexpression may enhance the expression of PD-1 or CTLA4, which suggested its potential as an important predictive biomarker for immunotherapy response in penile cancer patients." (PMID 38774752, 2024). "The prognostic significance of PD-1 target and CTLA-4 target expression in penile cancer has not been confirmed by research." (PMID 39087027, 2024). "There are also several other checkpoint molecules that could prove to be important as prognostic and predictive biomarkers in penile cancer, such as CTLA-4, TIM3, and LAG3, molecules that were not included in this study but would be of great interest to investigate." (PMID 40822998, 2025).
Pleural effusion (4 papers, 2018 to 2025). The presence of an excessive amount of fluid in the pleural cavity. "High expression of soluble isoform of CTLA-4 in pleural effusions (>67 pg/mL) was significantly associated with a prolonged survival (adjusted HR (95% CI) 0.36 (0.17–0.76); p = 0.007)." (PMID 34206956, 2021). "High CTLA-4 expression in pleural effusions, biopsy and blood samples was found to be associated with a better OS compared to patients with low expression of CTLA-4." (PMID 34206956, 2021). "Soluble isoform of CTLA-4 was also studied in the blood samples and pleural effusions on these patients." (PMID 34206956, 2021). "Both serum and pleural effusion were found to express soluble CTLA-4 (Pearson’s correlation coefficient of 0.52)." (PMID 34206956, 2021). "More importantly, compared to the Tregs in the pleural effusion of HP, the Tregs in the MPE of LCP exhibited higher expression levels of CTLA4, TIGIT, and BATF." (PMID 40959273, 2025).
Primary hypothyroidism (4 papers, 2019 to 2024). A type of hypothyroidism that results from a defect in the thyroid gland. "Primary hypothyroidism was associated with anti-PD-1 inhibitors; pembrolizumab and nivolumab and with combination anti-PD-1 and CTLA4 inhibitor therapy (nivolumab plus ipilimumab)." (PMID 38681767, 2024). "Only one of 120 patients receiving anti‐CTLA4 monotherapy developed primary hypothyroidism." (PMID 31518074, 2019).
pyrexia (4 papers, 2020 to 2024). "The increased risk of pyrexia for all grades is only found when PD-1/PD-L1 plus cytotoxic T lymphocyte-associated protein 4 (CTLA-4) was compared to CTLA-4 [odds ratio (OR) = 2.48, 95% CI: 1.17, 5.23]." (PMID 33194659, 2020). "Programmed cell death 1 (PD-1)/CTLA-4 had the highest risks of high-grade pyrexia (1.14%) and rash (0.94%)." (PMID 33178599, 2020). "Fever is more prevalent in IMHs induced by anti-CTLA-4 inhibitors." (PMID 38398187, 2024).